NCAN (neurocan)
Diseases named in the same sentence as NCAN in open-access papers (continued):
Sharing a sentence is not in itself a finding about the gene and the disease.
dyslipidemia (1 paper, 2020). "Some previous studies have established that the 19p13.11 locus linked together the adjoining genes NCAN and PBX4 with dyslipidemia, and these relationships may now be attributed to TM6SF2." (PMID 32568739, 2020).
Gliosis (1 paper, 2017). Gliosis is the focal proliferation of glial cells in the central nervous system. "Markers indicative of gliosis were further investigated by examining patterns of immunoreactivity for GFAP, S100-β, and neurocan (NCAN)." (PMID 28381236, 2017).
Intraventricular hemorrhage (1 paper, 2023). Bleeding into the ventricles of the brain. "Similarly, there is an upregulation of aggrecan, brevican, neurocan and versican in rabbit pups after intraventricular hemorrhage." (PMID 38025264, 2023).
ischemic brain disease (1 paper, 2024). "In CNS, miR‐24 has been documented to have an anti‐hypoxic effect by downregulating the expression of neurocan, which could be protective against neuron cell apoptosis in ischemic brain disease role in cognition and neuroinflammation." (PMID 39440167, 2024).
manic episodes (1 paper, 2020). "In human genetic studies, the risk allele for NCAN was significantly associated with the presence of manic episodes." (PMID 32306996, 2020).
retinal degeneration (1 paper, 2022). Degeneration of the retina. "In contrast, we did not observe any upregulation of Neurocan with progressive retinal degeneration." (PMID 35508614, 2022).
retinal ischemia (1 paper, 2023). A ischemic disease that involves the retina. "Increased NCAN levels have been detected in a retinal ischemia model in the rat." (PMID 37146093, 2023).
Stroke (1 paper, 2025). Sudden impairment of blood flow to a part of the brain due to occlusion or rupture of an artery to the brain. "Ten proteins (including BCAN, NCAN, beta-NGF, SIGLEC1 and VWC2) were common to both the acute and convalescent stroke phase, but there were also differing examples." (PMID 40316737, 2025).
vascular dementia (1 paper, 2021). A degenerative vascular disorder affecting the brain. "We recently reported that CSF brevican and neurocan peptide concentrations were decreased in vascular dementia compared with healthy controls, and thus it was of interest to explore their levels in iNPH patients who showed vascular-based pathology." (PMID 33985551, 2021).
tumor (9 papers, 2017 to 2025). "Increased NCAN expression was associated with presence of Merkel cell polyomavirus DNA (p = 0.001) and viral large T antigen expression in tumor tissue (p = 0.004) and with improved MCC-specific survival (p = 0.027) and overall survival (p = 0.034)." (PMID 37146093, 2023). "To clarify the mechanisms underlying the induction of tumor sphere formation by NCAN and the potentiation of the malignancy of NB cells by NCAN, we investigated the comprehensive mRNA expression pattern by performing a DNA microarray analysis." (PMID 29290949, 2017). "Exogenously expressed (i.e., overexpressed, recombinant protein, and conditioned media) NCAN induces adherent NB cells to form spheroids and develop tumour in vivo, in which both the chondroitin sulphate glycans and the core protein of NCAN are involved." (PMID 38791985, 2024). "To conclude, we discovered that NCAN is frequently expressed in MCC, and its expression is associated with presence of MCPyV in tumor cells and improved disease outcome." (PMID 37146093, 2023). "In contrast, downregulation of NCAN in the TH-MYCN-mouse-derived tumor cells impaired their proliferation and abolished tumorigenic potential." (PMID 36231134, 2022). "NCAN mRNA was also ubiquitously expressed in the neuroblasts occupying the terminal tumor tissue of hemizygotes." (PMID 29290949, 2017). "Taken together, these findings led us to conclude that both the CS sugar chains and the core protein of NCAN were necessary for the induction of tumor sphere formation." (PMID 29290949, 2017). "Lastly, we addressed the involvement of NCAN in the formation of tumor spheres derived from TH-MYCN mice." (PMID 29290949, 2017). "The knockdown of NCAN in tumor sphere cells cultured from TH-MYCN mice resulted in growth suppression in vitro and in vivo." (PMID 29290949, 2017). "To further evaluate the involvement of NCAN in mouse tumor sphere cells, we carried out allografts in which the mouse tumor sphere cells were subcutaneously inoculated into the same strain of wild-type mice." (PMID 29290949, 2017). "NCAN was also highly and ubiquitously expressed in the early lesions and terminal tumor of TH-MYCN mice, a NB model." (PMID 29290949, 2017). "We can thus conclude that NCAN is highly expressed and secreted from NB tumor cells all through the tumorigenic process." (PMID 29290949, 2017). "To further test the NCAN-induced tumor sphere formation, we treated TNB1 cells with human recombinant NCAN protein and then examined the phenotype." (PMID 29290949, 2017). "Because NCAN consists of core protein and CS sugar chains, we next addressed the contribution of those components to tumor sphere formation." (PMID 29290949, 2017). "The authors hypothesized that NCAN may be a pivotal component of the tumor stem cell niche and can be involved in maintenance of the undifferentiated phenotype of NB cells." (PMID 36231134, 2022). "Exogenous NCAN expression transforms adherent NB cells into spheroids with high malignancy potential both in vitro (anchorage-independent growth and chemoresistance) and in vivo (xenograft tumor growth)." (PMID 32231047, 2020). "In addition, the NCAN-expressing tumor sphere cells exhibited a potentiated tumor-forming ability in vivo when they were subcutaneously inoculated into nude mice." (PMID 29290949, 2017). "Because NCAN induced both tumor sphere formation and the expression of stemness-related genes, our findings suggest that NCAN may function as a component of the extracellular matrix, which comprises the particular environment for stem cells, i.e., the niche." (PMID 29290949, 2017). "Interestingly, exogenous NCAN (i.e., overexpression, recombinant protein and conditioned medium) transformed adherent NB cells into spheres whose malignancies in vitro (anchorage-independent growth and chemoresistance) and in vivo (xenograft tumor growth) were potentiated." (PMID 29290949, 2017).
tumor (continued). "As a result, the control tumor sphere cells developed subcutaneous tumors at a certain frequency, whereas the NCAN-knocked down cells could not form subcutaneous tumors at all." (PMID 29290949, 2017). "Importantly, NCAN, as a component of extracellular matrix, is reported to bind to HSPGs including glypican-1 and syndecan-3 and FGF2 via its C-terminal domain, which was shown to be essential for tumor sphere formation in our experiments." (PMID 29290949, 2017).
cancer (6 papers, 2017 to 2025). A tumor composed of atypical neoplastic, often pleomorphic cells that invade other tissues. "Contrary to our finding in MCC, NCAN expression has earlier been associated with poor outcome and progression in cancer." (PMID 37146093, 2023). "Previous reports mentioned that the mRNA of NCAN was detected in neoplastic mammary glands in mice, and that it was significantly increased in several cancer types." (PMID 29290949, 2017). "Our findings suggest that NCAN, which stimulates NB cells to promote malignant phenotypes, is an extracellular molecule providing a growth advantage to cancer cells." (PMID 29290949, 2017). "However, our present study appears to be the first to address the actual function of NCAN in cancer." (PMID 29290949, 2017). "Next, according to the mRNA expression level in various cancer types derived from the Cancer Cell Line Encyclopedia, the high mRNA expression of NCAN was almost unique to NB compared to other cancer cell types, whereas the expression of VCAN was not specific nor the highest in NB." (PMID 29290949, 2017). "Therefore, the observed downregulation of BCAN, NCAN, and VCAN in Etoposide resistant RB cells contrasts with the expression pattern in adult cancer but might represent the expression pattern in childhood tumors." (PMID 32560557, 2020).
brain diseases (2 papers, 2014 to 2025). "Apart from NCAN, the other proteins are also relevant to the central neural system and brain diseases." (PMID 40456753, 2025). "In the next section we will present changes in NCAN structure able to induce brain disorders." (PMID 24955366, 2014).
heart disease (1 paper, 2019). "A number of studies have proposed the contribution of versican in ECM remodeling and heart disease, but the role of aggrecan (a cartilage proteoglycan with potential role in vascular stiffness), neurocan (specific to neuronal tissue), and brevican in heart disease remains unexplored." (PMID 31547598, 2019).
neurodevelopmental disorder (1 paper, 2018). A behavioral and cognitive disorder with onset during the developmental period that involves impaired or aberrant development of intellectual, motor, or social functions. "The involvement of Neurocan in regulating synapse remodeling on both excitatory and inhibitory neurons makes it an important candidate molecule for neurodevelopmental disorders with aberrant spine and synapse numbers that could impact cortical excitatory/inhibitory balance." (PMID 30356641, 2018).
NCAN also shares sentences with these, for which no sentence is quoted: Hepatic steatosis (4 papers); depression (3); autism spectrum disorder (2); Cirrhosis (2); glioblastoma (2); Hepatic fibrosis (2); mood disorder (2); alcoholic cirrhosis (1); amyloid (1); breast carcinoma (1); colon cancer (1); connective tissue disorder (1); delirium (1); episodic ataxias (1); fibrosis (1); Focal cortical dysplasia (1); genetic disorder (1); infection (1); Intellectual disability (1); ischemia (1); liver cancer (1); liver cirrhosis (1); lung carcinoma (1); melanoma (1); nephropathies (1); nephrotic syndrome (1); non-alcoholic steatohepatitis (1); Obesity (1); prostate carcinoma (1); temporal lobe epilepsy (1).
A further 1 disease shares a sentence with NCAN in 1 paper.